CD4 (CD4 molecule)
Diseases named in the same sentence as CD4 in open-access papers (continued):
Sharing a sentence is not in itself a finding about the gene and the disease.
tumor (continued). "The presence of T regulatory cells (Tregs) was significantly increased in tumor samples in three T-cell subpopulations: CD4+ (p < 0.0001), CD8+ (p < 0.0001) and CD4+CD8+ (p < 0.01)." (PMID 36551555, 2022). "The density of FoxP3- CD4+ helper T cells, CD137+ CD8+ cytotoxic T cells, and CD137+ CD4+ T cells seemed to be numerically higher in the tumor margin than in the stroma or center." (PMID 36237314, 2022). "Particularly, CD4+ Treg cells have been found to possess a great immunosuppressive role and enable the progression of the tumor through inhibiting effectual antitumor immunity." (PMID 35855850, 2022). "In patients with low-risk group, a higher infiltrating abundance of CD8+ T cells and resting memory CD4+ T cells were found, which contributed to the anti-tumor immunity and were positively correlated with prognosis." (PMID 36277284, 2022). "With ART, the patient’s CD4 count increased slowly; however, the size of the T11 paraspinal tumor also increased slowly and reached a maximum size of 13 cm3 while the CD4 count remained at approximately 108 cells/μL." (PMID 35141174, 2022). "We postulate cytotoxic CD4+ T cells mediate anti-tumor activity via HLA-II on tumor cells and augment HLA-I-dependent cytotoxic CD8+ T cell interactions to drive ICB response in NSCLC." (PMID 35831288, 2022). "The expression of VISTA on CD4+ T cells in tumor tissue showed low secretion of cytokines including IFN-γ, IL-2, IL-4, IL-10, IL-17, and IL-12p70." (PMID 35122478, 2022). "Another approach of great interest is the use of personalized cell therapy that uses tumor neoantigens to stimulate CD4/CD8 cells to recognize MCC." (PMID 36844955, 2022). "Both of these proteins have been shown to be expressed on tumour-infiltrating regulatory CD4 + FOXP3+ T cells (Treg) and Th1 CD4+ T cells, respectively, suggesting a potential role in immune escape and/or evasion." (PMID 35327375, 2022). "CD4+ T cells have tumor-specific states, and multiple cytotoxic CD4+ T cells have been cloned and amplified." (PMID 36059506, 2022). "CD8+ T lymphocytes identify and kill tumor cells playing a role in the anticancer immune response, and are usually supported by CD4+ T helper cells that release interferon-gamma (IFNγ) and interleukin-2 (IL-2)." (PMID 35958590, 2022). "Both the proliferative state and clonal expansion, as well as their presence near MHC class II+ cells in the TME suggest that DP CD4+ Th TILs recognize tumor antigens." (PMID 35439168, 2022). "Tregs secrete interleukin-10, -35, and transforming growth factor− (TGF−) in order to suppress the anti-tumor immune response mediated by NK cells, CD4+ T cells, and CD8+ T cells." (PMID 35479081, 2022). "The relationships between 4 top hub genes and tumor-infiltrating immune cells including B cells, CD4+ T cells, CD8+ T cells, neutrophils, macrophages, and dendritic cells were carried out based on TIMER." (PMID 35093172, 2022). "NSCLC tumors with a high number of Meflin+ CAFs exhibited increased CD4+ T-cell infiltration and areas of tumor vessels, suggesting the involvement of Meflin+ CAFs in multiple aspects of the TME." (PMID 35236758, 2022). "Correlations between frequencies of FoxP3+ Tregs and CD4+PD-1+ T cells in TME were stronger in early tumor stages, compared to advanced stages (r = 0.675, p = 0.045 [early]; r = 0.489, p = 0.089 [advanced])." (PMID 36146549, 2022). "The DP CD4+ Th TILs were proliferating in the tumor, as illustrated by increased frequencies of cells expressing Ki-67, which was mainly exclusive to that subset." (PMID 35439168, 2022). "Narayanan and colleagues demonstrated that irreversible electroporation (IRE) of KPC4580P tumors induces complete regression in a subset of tumor-bearing animals and the antitumor responses are CD4/CD8 T cell-dependent." (PMID 36569934, 2022). "This leads to IL‐1β secretion, which stimulates CD4+ T lymphocytes to produce IL‐17, potentially leading to angiogenesis and subsequent tumor relapse." (PMID 35067006, 2022).
tumor (continued). "They found that tumor-infiltrating CD4+ Thigh cell was an independent prognosticator helpful in evaluating the immune microenvironment of PDC." (PMID 35711924, 2022). "First, APOBEC1 was negatively correlated with the infiltration level of many kinds of immunoreactive tumor-infiltrating cells, including Tem_CD4, Tem_CD8 and NK cells, and negatively correlated with the expression level of most immune promoters." (PMID 36339709, 2022). "We defined expression of high levels of PD-1 and that of CD39 in tumor-infiltrating CD4 T cells as markers of terminal exhaustion and of tumor Ag specificity." (PMID 35954341, 2022). "Naïve CD4+ T cells differentiate into T helper 1 (Th1)-oriented TFH cells that produce CXCL13 in tumor microenvironments after being primed by antigen-presenting cells in the lymph node." (PMID 35053457, 2022). "The heat map and violin diagram indicate that the distribution of macrophages, B-cells, and CD4 cells have significant differences between tumor tissues and normal tissues." (PMID 36172179, 2022). "High fractions of activated memory CD4 T cells were known to have an anti-tumor function, while high fractions of activated mast cells and M2 macrophage have a pro-tumorigenic effect, and are associated with poor prognosis." (PMID 36555319, 2022). "In short, anti-tumour effector cells, including CD4+ helper T cells and CD8+ cytotoxic T cells, in addition to the ratio of CD8+ cytotoxic to FOXP3+ T regulatory (Tregs), are associated with better patient prognosis and response." (PMID 36139665, 2022). "Bacterial‐induced tumor enlargement was attributed to the inhibition of T cell recruitment into the tumor site as evidenced by the fewer number of CD4+ and CD8+ T cells detected in the tumors of F. nucleatum‐infected mice." (PMID 35244982, 2022). "The higher the CD8+ + CD4+ value, the stronger the immune effect on the tumor, and the higher the SR of patients." (PMID 36124030, 2022). "The data on anti-RANKL/anti-PD1/anti-CTLA4 combination therapy showed promising results in a higher proportion of tumor-infiltrating CD4+ and CD8+ T cells that can produce both IFNγ and TNFα after anti-RANKL treatment." (PMID 35386705, 2022). "It has been noted that some patients with RCC experience a rapid increase in the number of CD4+ lymphocytes infiltrating the LAG-3+ tumor." (PMID 36077354, 2022). "In contrast, Th2 cells as one type of CD4+ T cells play an important role in provoking profound tumor angiogenesis." (PMID 36439137, 2022). "They possess antitumor properties by which they guide the CD8+ T cells into the tumor site to induce apoptosis of tumor cells, attract CD4+ T cells to reduce angiogenesis and suppress cell proliferation." (PMID 35083488, 2022). "On the other hand, it has been demonstrated that intratumor MDSCs mainly hamper CD8+ T cell activation, which t suppresses tumor cell escape from the immune system; however, the ability of MDSCs to elicit CD4+ T cell tolerance is still debated and unclear." (PMID 35089465, 2022). "Abemaciclib combined with DOX results in much greater efficacy than DOX alone in inhibiting tumor growth; it acts by suppressing the CD4/6-Cyclin D-Rb pathway." (PMID 36176756, 2022). "We performed polyclonal functional assays testing the ability of GITRL to stimulate tumor-derived CD4+ and CD8+ TIL function ex vivo." (PMID 36155259, 2022). "To extend the finding, we herein validated that eHSP90α-induced M2-polarized macrophages exhibited a tumor-promoting activity and the promoted tumor tissues had significant increases in microvascular density but decreases in CD4+ T-cell level." (PMID 35053345, 2022). "Recently, our research has shown that NCTD can increase the tumor infiltration of CD4+/CD8+ T in prostate cancer." (PMID 35409302, 2022).
tumor (continued). "For the first time, we report that a high frequency of circulating CD4+FoxP3+Helios+ Tregs was associated with poorer DFS, while a high frequency of tumor-infiltrating CD4+FoxP3−Helios− T cells was associated with poorer DFS." (PMID 35655158, 2022). "The antitumor activity of IL12 is mainly mediated by tumor infiltration and activation of CD4+ and CD8+ T cells." (PMID 36405748, 2022). "We have also demonstrated that the prevalence of CD3−/CD94+ NK cells and CD8+ cytotoxic T cells were greater in advanced tumor stages, whereas that of CD4+ T helper cells was decreased." (PMID 36428793, 2022). "The presence of tumor-associated macrophages 2 (TAM2) with CD4+ T lymphocytes releasing IL4 and myeloid-derived suppressor cells (MDSCs) moves the TME in favor of tumor immune scape." (PMID 36552048, 2022). "According to the RNA-seq analysis, we explored the relationship between HNRNPC and tumor-infiltrating CD8 or CD4 positive T cells." (PMID 36536402, 2022). "Correlations between frequencies of FoxP3+Helios+ Tregs and CD4+TIM-3+ T cells in TME were stronger in advanced tumor stages, compared to early stages (r = 0.793, p = 0.011 [early]; r = 0.771, p = 0.002 [advanced])." (PMID 36146549, 2022). "Another study found increased CD4+ memory activated T cells in T1-2 tumors compared to T3-4, as well as in tumor involved tissue compared to uninvolved tissue; however, this study did not assess for sex-related TME differences in CRC." (PMID 36387163, 2022). "Altogether, CRT seems to improve the anti-tumor immune response in the TDLN by promoting activation of helper CD4+ and cytotoxic CD8+ T lymphocytes, and downregulating Tregs." (PMID 35566403, 2022). "On the other hand, stimulation with CD134 and CD137 agonists to boost Eomes expression in CD4 T cells was found to improve outcomes in a mouse model of tumor immunity; an outcome that correlated with increased anti-tumor CD8 T cell responses." (PMID 36358898, 2022). "Foxp3- CD4+ helper T cells have been shown to promote the priming of tumor-specific CD8+ T cells and help elicit durable T cell responses by interacting with dendritic cells in an MHCII-dependent manner." (PMID 36237314, 2022). "It has been previously reported that the frequency of CD4+CD25+Foxp3+ Treg cells is amplified in the tumor micro-environment and peripheral blood mononuclear cells, indicating that the enhancement of Treg cells is a widespread problem." (PMID 35606804, 2022). "DCs are the utmost powerful specialized antigen presentation cells (APCs) since they uptake, process, and present antigens, such as tumor antigens, to trigger naïve antigen-specific CD4 and CD8 T cells and begin all adaptive immune responses." (PMID 36703982, 2022). "In a mouse model, the combined RT and anti-CD25/CTLA-4 monoclonal antibody decreased Tregs, PD1+CD8+, and PD1+CD4+ T cells, resulting in the suppression of both irradiated and distal unirradiated tumor resulting in improved OS and reduced liver metastasis." (PMID 35155221, 2022). "Here we review and discuss the evidence supporting the contribution of CD4 T cells to anti-tumor immunity, especially recent advances linking CD4 T cell subsets to efficacious PD-L1/PD-1 blockade immunotherapy." (PMID 36362027, 2022). "Conversely, S91 cells induced higher CD4+/CD25+ cell levels in AIRmin mice than in AIRmax mice after 7 days of tumor development." (PMID 35265317, 2022). "Baseline levels of tumor-infiltrating CD4+/CD8+ T cells, macrophage M1, and inflammatory cytokine secretion were implicated in immune response." (PMID 35155238, 2022). "TSLP exerts its dominant anti-tumor effects through the induction of CD4+ Th2 cell immunity in the early stages of keratinocyte cancer development." (PMID 35432341, 2022). "Our previous studies demonstrated that CD4+ T cells can uptake tumor antigen and antigen-presenting molecules from dendritic cells-derived exosomes and inducing antitumor immunity." (PMID 36466863, 2022).
tumor (continued). "Investigation of the tumor microenvironment showed significant CD4 infiltration as well as enhanced Th1 and cytotoxic CD8 T activation." (PMID 35651802, 2022). "TIM-3 was significantly upregulated on the surface of tumour-infiltrating CD4+ T cells and CD8+ T cells compared with circulating levels post-FLOT (p = 0.007)." (PMID 35366537, 2022). "Our results showed that CD4+ TLEX-CD8086 cells more effectively attenuated tumor growth and prolonged the survival time of L1210 cell-bearing mice than LEX-CD8086 and CD4+ TLEX-null cells did." (PMID 36466863, 2022). "The CD4+ T cells can exert anti-tumor or pro-tumor effects in an environmental dependent manner according to differentiations into T helper cells or T regulatory cells." (PMID 36527157, 2022). "Increased CTLA-4 expression in circulating CD4+ T cells from colorectal cancer patients was found to be positively correlated with tumor-node-metastasis (TNM) staging." (PMID 36612180, 2022). "Tumor whole-cell vaccine contains a full range of tumor-associated antigens (TAA) and is rich in CD8+ T cells and CD4 helper T-cell epitopes." (PMID 35664731, 2022). "The percentage of total CD4+ Th cells remained relatively unchanged in the tumor, blood, and other peripheral tissues, with modest increases detected in the spleen and bone marrow at d 14 and 21, respectively." (PMID 36142210, 2022). "The murine tumors showed that TDO2+ myofibroblasts were also mainly located in the distal area of the tumor nests and that CD4+ and CD8+ T cells were mainly located around TDO2+ myofibroblasts, consistent with the results observed in human OSCC tissues." (PMID 35972800, 2022). "Other tumor-associated immune-cell populations such as myeloid-derived suppressor cells (MDSC), CD8+ cytotoxic T cells, and CD4+ T-helper cells remained unchanged among all three groups of mice." (PMID 35577388, 2022). "It is important to note the emerging role of CD4+ T cells in antitumor immunity, and in particular, their functional versatility in the context of the tumor immune microenvironment." (PMID 35565302, 2022). "In our study, CD4+ T cells were the major tumor-infiltrating T cell subset, mostly consisting of CD4+ Tconv cells." (PMID 36509285, 2022). "In CRC, TAMs showed pro-inflammatory properties and expressed cytokines such as IFNγ, IL6 and IL1, which activated type-1 polarised CD4+- T cells (Th1) cells mediating an anti-tumour immune response." (PMID 36497148, 2022). "Type I cytokines secreted by CD4 T-cells homing to tumor will enhance the cross-priming of CD8 T-cells." (PMID 35948756, 2022). "Without treatment, all mice died around 20 days after injection of tumor cells; however, transfer of activated tumor-specific CD4+ T cells significantly prolonged mouse survival." (PMID 35784297, 2022). "The frequencies of total CD4+ T cells remain similar when comparing lymph node cells from naive (nLN) and tumor mice (TdLN) (∼25%), while in the TILs, the frequency of total CD4+ T cells is considerably lower (∼10%)." (PMID 35860556, 2022). "In the tumor microenvironment, lymphocytes represented by CD4+ Th cells, CD8+ cytotoxic T cells and CD4+/CD25+/FoxP3+ Tregs are important components of the immune response." (PMID 35928818, 2022). "Similar findings support the critical involvement of tumor-specific CD4+ T cells in non-small cell lung cancer." (PMID 35214655, 2022). "They further regulate the activity and anti-tumor immune response of NK cells and CD4+ T cells via various mechanisms." (PMID 36072581, 2022). "In secondary lymphoid organs, CD4+ T cells can inhibit or stimulate the activity of anti-tumor cytotoxic T cells, hence modulating tumor cells." (PMID 35957907, 2022). "CD4-positive T cells recognize tumor antigens via MHC class II and assist CD8-positive T cells in antitumor immunity." (PMID 36361781, 2022).
tumor (continued). "CD1d and CD4 antibody showed the most obvious abolishment which indicates that NKT cells played a more critical role during the anti-tumor process than the CD8+ T-cells." (PMID 34983554, 2022). "In support of the immunomodulatory function of vitamin C, flow cytometry analysis of tumors showed that vitamin C treatment induced tumor infiltration by both CD4+ and CD8+ T lymphocytes and increased the CD8+/CD4+ ratio." (PMID 35173532, 2022). "They divided patients’ tumors into those with a high level of CD4+ tumor-infiltrating lymphocytes (TILs) and those with minimal infiltration." (PMID 35053457, 2022). "As expected, the more tumor infiltration of CD4+ T cells and CD8+ T cells were distinctly observed in the PCN-ACF-CpG@HA group under laser irradiation." (PMID 35910806, 2022). "At the same time, CD4+ T cells themselves can produce cytokines to participate in the suppression of tumor cells, such as γ-interferon (IFN-γ), tumor necrosis factor-α (TNF-α), and IL-17." (PMID 35454171, 2022). "Regulatory T cell subsets (Tregs) characterized by the expression of CD4 and FoxP3 generally dampen the anti-tumor immune response." (PMID 36612283, 2022). "CD4 responses have been shown to have an increasingly important role in anti-cancer immunity and our work and that of others has shown that CD4 responses can directly mediate tumour therapy in mouse models." (PMID 36544781, 2022). "According to the obtained results, the low-risk group exhibited more infiltration of CD8+ T cells, memory activated CD4+ T cells, and plasma cells, as well as higher immune score, and thus can be categorized as “hot” tumor phenotype." (PMID 35938006, 2022). "CD8+ T cells, also known as cytotoxic T lymphocytes (CTLs), are the primary immune cells responsible for destroying tumor cells, whereas CD4+ T cells help B cells produce antibodies and perform other immune regulatory functions." (PMID 36465180, 2022). "Activated CD4+T memory cells play a key role in generating effective anti-tumor immunity through multiple mechanisms such as enhanced antigen presentation, co-stimulation, T cell homing, T cell activation, and effector functions." (PMID 35102149, 2022). "In TME, CD8+ T cells assume the role of killing tumor cells, while Treg is the most representative CD4+ immunosuppressive cell." (PMID 36341377, 2022). "What’s more, we found that risk score calculated by the signature was positively correlated to tumor purity, CD4+ naive T cells, and negatively correlated to CD8+ T cells." (PMID 35494024, 2022). "CD4+ T cell is an important immune cell in human immune system; it is mainly expressed in helper T (Th) cells and played an indispensable role in tumor immunity." (PMID 35465267, 2022). "We found PDAC to be highly infiltrated by Tregs, which account for approximately 20% of all tumor-infiltrating CD4+ T cells." (PMID 36509285, 2022). "NACT proved their role in the induction of many local changes of the tumor microenvironment including activation of CD4+ and CD8+ T cells." (PMID 35138498, 2022). "The infiltration scores of anti-tumor immune cells including activated B cells, activated CD4+ T cells, activated CD8+ T cells, natural killer cells, and activated dendritic cells (DC) increased in the mutation group." (PMID 36038820, 2022). "Within the tumor microenvironment, CD4+ and CD8+ T cell-mediated Th1 immune responses act as the dominant antitumor immune mechanisms." (PMID 35865946, 2022). "This is achieved via cross-presentation by MHC-I and MHC-II of tumour-derived antigens to CD8+ T cells or CD4+ T cells, respectively." (PMID 35406451, 2022). "In contrast, the levels of anti-tumor immune cells, such as CD8 + T cells and activated memory CD4 + T cells were increased in the low-risk group." (PMID 35372408, 2022). "CD4+ PD-1− TILs significantly increased on both sides of tumor after treatment with either C-REV alone or combined." (PMID 36513720, 2022).